CD24 (CD24 molecule)
Diseases named in the same sentence as CD24 in open-access papers (continued):
Sharing a sentence is not in itself a finding about the gene and the disease.
breast cancer (continued). "Similarly, IL-6 stimulation of CD44-CD24+ breast cancer patient derived cells has been demonstrated to reduce E-cadherin expression and generate a CD44 + CD24- population." (PMID 26522776, 2015). "Because the targeting of CSCs has been viewed as an important strategy for long-lasting treatment, a number of studies have focused on the identification of CSC markers such as CD44, CD24, epithelial cell surface antigen (ESA), and aldehyde dehydrogenase 1 (ALDH1) in breast cancer." (PMID 26528725, 2015). "So far, 3,144 m/z (CD24) expression in serum samples from breast cancer patients with positive lymph nodes has not been reported." (PMID 25511546, 2015). "CD24− and CD44+ cells have been putatively identified as breast cancer stem cells." (PMID 26694341, 2015). "In a parallel experimental set using the razor-wound migration assay method, human breast cancer cell line MCF-7 furnished higher expression of CSC-markers (that is, CD44+/CD24-/low) in the migrating population as compared with the non-migrating fraction of cells as evident from our confocal data." (PMID 25315241, 2014). "It was reported that CD44+ progenitor-like cells of normal mammary epithelium were globally hypomethylated compared to luminal epithelial (CD24+ and MUC1+) and myoepithelial (CD10+) cells and cell type-specific methylation patterns were conserved in breast cancer." (PMID 24971511, 2014). "It was clear, however, that the CD44+CD24-/low surface markers enrich for tumorigenic cells in some, but not all, breast cancers." (PMID 25928070, 2014). "Since the CD44+/CD24-/low antigenic phenotype does not constitute a universal antigenic phenotype of TICs in all breast cancer subtypes, it is necessary to identify novel TIC markers in order to better define this phenotype." (PMID 25216750, 2014). "CSCs have been identified and isolated from various tumors using specific cell surface markers, including CD44 for head and neck cancer, CD133 for prostate cancer, CD90 for liver tumor, CD24 for ovarian cancer, CD133 for brain tumor, CD44+CD24−/low for breast cancer, and CD133 for lung cancer." (PMID 24955581, 2014). "In human breast cancer, it has been shown that breast CSCs have a CD44+/CD24- phenotype." (PMID 23799994, 2013). "Using flow cytometry, CSCs were detected in canine mammary tumors as cells CD44+ and CD24-." (PMID 24119896, 2013). "Finally, more recent molecular studies have shown that some forms of malignant tumours, including breast cancer, arise from a small subset of cancer stem cells (CSCs), which are often marked by the cell surface antigens CD133, CD144 and CD24." (PMID 23343205, 2013). "In addition, we observed that LLL12 inhibited cell viability and tumorsphere forming capacity in the ALDH+/CD44+/CD24+ subpopulation of MDA-MB-231 and SUM159 breast cancer cells." (PMID 24376586, 2013). "Recent experimental evidence suggests ALDH-positive (ALDH+), or cell surface molecule CD44-positive (CD44+) but CD24-negative (CD24−) breast cancer cells have cancer stem cell properties." (PMID 24376586, 2013). "In vitro, Ca1a, MCF7, Sum159, and MDA-MB-231 breast cancer lines, sorted CD44+CD24+ non-invasive cells could give rise to invasive CD44+CD24− cells (and vice versa), even when initially plated as single cell clones." (PMID 23986719, 2013). "We found that the proportion of CD44+/CD24- tumor cells was similar in breast cancer samples with and without basal-like features (11.93% versus 18.44%, p = 0.143)." (PMID 22762532, 2012). "These two indicators for LN metastasis of breast cancer markers may only relate to the distribution of organs, while CD44+CD24-/low cells not only relate to the distribution of organs, but also to their biological characteristics (invasiveness)." (PMID 23046710, 2012). "On breast cancer cells, CD24 acts as a P-selectin ligand but not an E-selectin ligand, and Mac-2bp acts as an E-selectin ligand." (PMID 22934288, 2012).
breast cancer (continued). "In this regard, breast cancer epithelial cell lines (specifically including MCF10A cells) have been shown to exhibit heterogeneous staining for CD44, CD24, and epithelial specific markers, which presumably correlates with the heterogeneous VIM staining in the parental control MCF10A cells." (PMID 22761798, 2012). "The relevance of this marker combination has been confirmed for breast tumor cells lines, although the percentage of putative CD24−/CD44+ breast cancer tumorsphere TICs did not correlate with tumorigenicity." (PMID 23042145, 2012). "Tumorigenic breast cancer cells that express high levels of CD44 and low or undetectable levels of CD24 (CD44+/CD24-/low) may be resistant to chemotherapy and therefore responsible for cancer relapse." (PMID 22839505, 2012). "A higher proportion of CD44+/CD24− tumour cells and ALDH1 positivity in pre-chemotherapy tissue was correlated with higher histologic grade, oestrogen receptor (ER) negativity, high Ki-67 proliferation index and basal-like subtype of breast cancer." (PMID 21559013, 2011). "Our studies confirmed that SP cells sorted by flow cytometry from human breast cancer cell line MCF-7 showed high expression of CD44+CD24- cells and had greater tumorigenicity than non-SP and unsorted cells, which indicates SP cells enrich CSCs." (PMID 22032476, 2011). "Breast CSCs, or tumor-initiating cells, can be isolated by the immuno-sorting of breast cancer cells that express the hyaluronian receptor CD44, a gene that is overexpressed in basal-like tumors and lack the expression of CD24, an endogenous inhibitor of the chemokine receptor CXCR." (PMID 24281098, 2010). "Thus, what are the potentially important differences between invasive and non-invasive breast cancer cells, and are the differences related to EMT or CD44/CD24 expression?" (PMID 20696077, 2010). "Actively growing CD24-/low/CD44+ non-adherent mammospheres were isolated from monolayer cultures of MCF-7 breast cancer cells according to published procedures, with some minor modifications." (PMID 20525204, 2010). "During our analysis of breast cancer cell lines for subpopulations with the CD44+/CD24- phenotype, we observed that almost all cell lines with a CD44+/CD24- subpopulation were basal breast cancer cells that had undergone epithelial to mesenchymal transition (EMT)." (PMID 20691079, 2010). "In this study we used two different, and independent, CICs markers (CD24-/low/CD44high and lack of proteasome activity) to confirm our previous observation that breast cancer cells are highly enriched for CICs after fractionated radiation." (PMID 20158881, 2010). "In a mammosphere assay, MCF-7-SLUG cells formed more and larger mammospheres compared to MCF-7-pQXIN cells, suggesting SLUG may confer a CSC phenotype to luminal breast cancer cells and these putative CSCs are phenotypically CD44+/CD24+." (PMID 20691079, 2010). "CD44+/CD24- and CD133 have been reported as TIC markers for breast cancer." (PMID 20727204, 2010). "It has been observed that basal-like breast cancers might be enriched with CD44+/CD24− cells, and an overlap between CD44+/CD24− cells and ALDH1-positive cell populations were described." (PMID 20010944, 2010). "Unlike M13SV1R2 cells, these R2d cells contain CD44+/CD24- cells previously identified as breast cancer stem cells and were responsive to estrogen for cell growth and tumor development." (PMID 21044318, 2010). "Both CD44+/CD24- and CD133 have been used as TIC markers for breast cancer and other malignancies." (PMID 20727204, 2010). "Nineteen breast cancer cells lines were initially screened for their expression of CD44 and CD24." (PMID 19906290, 2009). "In breast cancer, CD44+/CD24- population harbors stem cell properties." (PMID 19751508, 2009).
breast cancer (continued). "Staining of PE14 mammospheres for CD24 with either the SWA11 or ML5 antibody showed that CD24 was low or absent, as was also observed by Ponti and colleagues in mammospheres cultured from recurrent breast cancer or MCF7 cells." (PMID 18541018, 2008). "To evaluate whether tumorsphere formation indeed mirrors tissue regeneration in our breast cancer cell lines, we assayed the percentages of CD44+/CD24-/ESA+ cells in maturing tumorspheres." (PMID 18366788, 2008). "Since there was a clear correlation between the CD44+/CD24- status and the basal-like tumor subtype, we extended the immunohistochemical analysis to an additional TMA including tumors from BRCA1 hereditary breast cancer patients, known to be of predominantly basal-like phenotype." (PMID 18559090, 2008). "To determine whether Brca1 cell lines contain a distinct population of cancer stem cells, we examined expression of cell surface markers previously assigned to human breast cancer stem cells, namely CD44 and CD24." (PMID 18241344, 2008). "A correlation of the CD44+/CD24-/low phenotype to specific breast cancer subtypes has not yet been reported in human breast tumors." (PMID 18559090, 2008). "The biological effects of CD24 (FL-80) cross-linking on breast cancer cells have not yet been established." (PMID 18433506, 2008). "Interestingly, the HER2+ tumor subtype, generally considered an aggressive form of breast cancer, displayed a low frequency of tumors containing CD44+/CD24- cells and was in fact often positive for the CD44-/CD24+ phenotype." (PMID 18559090, 2008). "Whereas breast cancer cell lines without CD44+/CD24- cells lacked invasive capacity, those with CD44+/CD24- subpopulation (MDA-MB-231, MDA-MB-436, and Hs578T) exhibited invasion." (PMID 17062128, 2006). "To test the hypothesis that human breast cancer cell lines differ in the proportion of CD44+/CD24- cells, we characterized 13 breast cancer cell lines by flow cytometry for surface expression of CD44 and CD24." (PMID 17062128, 2006). "We compared the differential enrichment of miRNA in HER2+ EVs and CD24+ EVs between women with malignant and benign BI-RADS 4 lesions to previous studies that have reported differential enrichment of EV miRNA from total EV preparations in plasma EVs of women with breast cancer." (PMID 40405296, 2025). "In addition, previous studies have shown that the lack of CD24 in human breast cancer leads to favor tumor initiation and growth." (PMID 40783744, 2025). "The fact that CD24 is an important driver of cell proliferation in many types of cancer, including breast cancer, is consistent with its correlation with Ki-67, SKP2 expression, and the lack of p21 and p27 cell cycle checkpoints expression that we observed in our breast cancer samples." (PMID 40943144, 2025). "Herein, the authors explored the sensing of general exosome biomarkers (CD9, CD63, and CD81), and cancer-related biomarkers (CD24, CD44, CD54, CD326, and CD340) which could be identified on exosomal surfaces derived from the three distinct breast cancer cell lines (MCF-7, MDA-MB-231, and SK-BR-3)." (PMID 38425422, 2024). "The number of integrin β4+ CTCs expressing CD133 and ALDH1A1 stem markers but not CD44+CD24- was increased in metastatic breast cancer as well as in molecular subtypes of breast cancer with poor prognosis (luminal (HER2+) and TNBC) compared with luminal A/B (HER2−) subtype." (PMID 38250718, 2024). "In conclusion, the negative role of CD24 in breast cancer was evident." (PMID 38561760, 2024). "Notably, the absence of breast cancer stem cell-associated gene expression, particularly the CD44+CD24- phenotype was observed with salinomycin treatment, further emphasizing its specific action against CSCs." (PMID 39403386, 2024). "Namely, CD24 positive expression in CTCs with hybrid EMT phenotype was closely associated with stage, lymph node metastasis and tumor size, but not with distant metastasis in breast cancer patients." (PMID 38806508, 2024).
breast cancer (continued). "Indeed, a high CD44/CD24 ratio and ALDH1+ expression were found invariable in primary tumors, CTCs, and distant metastases, suggesting their stability during the development and metastasis of breast cancer." (PMID 36594086, 2023). "Moreover, recent studies suggest that CD24 + /CD49f + murine breast cancer cells and CD24-/CD44 + human breast cancer cells exhibit stem cell properties, also known as breast cancer stem cells or breast cancer stem-like cells." (PMID 38031089, 2023). "TNF-α treatment could switch the non-CSC (CD44+/CD24+) population to a CSC-like (CD44+/CD24−) population by increasing the expression of EMT factors in breast cancer cells." (PMID 36979874, 2023). "However, the overexpression of CD24 has been already observed in previous study reports in ovarian and breast cancer cells but it has not yet been declared which is the exact pathway that causes CD24-mediated immune resistance on TAM." (PMID 36109471, 2023). "Furthermore, we showed that HIF-2α, but not HIF-1α, was highly expressed in CD44+CD24− breast cancer tissues." (PMID 35301432, 2022). "In our results, high expression of MMP1, CD24, SDC1, and SPP1 correlated to the development of breast cancer, worse OS and immune cell infiltration, indicating that MMP1, CD24, SDC1, and SPP1 might be as the potential prognostic biomarkers and immunotherapy targets for breast tumor." (PMID 35037689, 2022). "Hence, further study is required to determine whether MMP1, CD24, SDC1, and SPP1 could be used as biomarkers or immune therapy targets in breast cancer." (PMID 35037689, 2022). "Breast cancer (BC)-initiating cells typically express high levels of CD44, a surface receptor for the extracellular matrix protein Hyaluronan, low levels of CD24, and exhibit high aldehyde dehydrogenase (ALDH) activity." (PMID 33785524, 2021). "Moreover, compared with normal tissues adjacent to cancer, the breast cancer tissues had significantly up-regulated protein expression levels of CD44, N-cadherin, and β-catenin, but significantly down-regulated protein expression levels of E-cadherin and CD24." (PMID 34932597, 2021). "Aberrant N-glycosylation at N52 of CD24 could account for the lack of CD24 expression at the cell surface of basal B breast cancer cells." (PMID 34360932, 2021). "The proportion of CD44+CD24− cell subsets in the serum‐free suspension culture of MCF‐7‐CSC was significantly higher than that of MCF‐7 (P < 0.05), indicating that the presence of surface markers of breast cancer stem cells in MCF‐7‐CSC had increased significantly than that of in MCF‐7." (PMID 33305893, 2021). "Triple negative breast cancer (TNBC) cells exhibit robust expression of CD24, suggesting that the inducible model described here mimics what is observed in human TNBC and may present a potential therapeutic opportunity for some SOX11+ breast cancers." (PMID 32909943, 2020). "Similarly, reduced E-cadherin and CD24 and increased vimentin, CD44, and Snail were also observed in MDA-MB-468 cells – another PTEN-negative breast cancer cell line with a 44-bp deletion in the PTEN gene, which results in frameshifting and loss of the PTEN protein 18,52." (PMID 32728066, 2020). "While low or absence of CD24 expression is one of the features of BCSCs, arising of CD24+ cell populations was reported from radiation-treated CD24−/low cells indicating a role of this protein in radio- and chemoresistance in breast cancer cell lines." (PMID 33327542, 2020). "Considering the conflicting nature of data regarding BCSC phenotypes, it is important to systematically investigate the expression of CD44, CD24 and ALDH1A1 in different breast cancer subtypes to understand whether the expression of these biomarkers indeed correlates with tumorigenic potential." (PMID 32423137, 2020).
breast cancer (continued). "In studies with breast cancer cell lines in vitro and in vivo, disulfiram not only diminished mammosphere formation and reduced CD44+CD24- and CD49f+CD24+ subpopulations, but also managed to reverse paclitaxel and cisplatin resistance of triple-negative breast cancer (TNBC)." (PMID 30967773, 2019). "In breast cancer, CD24 is negative in CSCs, and CD24-negative cells are tumorigenic and invasive." (PMID 30410672, 2018). "As expected exclusive c-CD24 expression in scrambled peptide treated becomes mostly m-CD24 in IRIS-inhibitory peptide treated MDA468 orthotopic mammary tumors (the non-uniform effect most likely is due to the intratumoral not systemic injection of the peptide)." (PMID 28052035, 2017). "To further validate TF expression on CSCs, we also used a CD44-based human CD24 negative CD44 positive (CD24- CD44+) breast cancer stem cell isolation protocol to isolate CD24- CD44+ CSCs from the TNBC line (MDA-MB-231) and patient-derived human breast cancer cells." (PMID 27903969, 2017). "In breast cancer, Mani and colleagues reported that the overexpression of Twist, Snail or FOXC2 not only made the breast cancer cells with more mesenchymal properties, but also with an increased expression of CD44+/CD24-/low breast CSC markers and an increased mammosphere forming efficiency." (PMID 28245823, 2017). "Thus, in addition to promoting CD24 internalization (this study), IRISOE by promoting EMT-inducers expression could enhance breast cancer TICs formation." (PMID 28052035, 2017). "Likewise, mesenchymal-like breast cancer cells that displayed higher resistance to radiation than their parental epithelial-like cells, were also found to exhibit a stem cell-like phenotype including a CD44+/CD24-/low molecular signature." (PMID 26988558, 2016). "However, recent evidence suggests BCSCs may exist in two distinct states, mesenchymal-like (CD44+/CD24-) and epithelial-like (ALDH+), which can interconvert in breast cancer." (PMID 27285982, 2016). "In addition, reports have confirmed that in both breast cancer-derived cell lines and breast tumors, CD44+CD24− phenotypes were not necessarily associated with patient outcome or the ability to metastasize." (PMID 25905435, 2015). "Our methylation analyses in breast cancer cells correspond with current data indicating that the promoter region of CD24 is unmethylated in breast cancer cells regardless of mRNA expression levels, indicating that other mechanisms are involved in the transcriptional regulation of CD24." (PMID 26444008, 2015). "Moreover, the IL-6/STAT3/JAK2 pathway is involved in the maintenance of stem cell–like cancer cells because CD44+CD24+ and CD44+CD24− breast cancer cells have high phospho-STAT3 via their expression of genes such as IL6, PTGIS, and HAS1, which activate an autocrine loop." (PMID 26515594, 2015). "Importantly, the same miRNAs were downregulated in CSCs from clinical breast cancer samples (lin-/CD44+/CD24-) compared to their non-tumorigenic counterparts." (PMID 25774169, 2015). "By combining the breast cancer model with periostin null mice, the authors could reveal that stromal periostin supports the survival and proliferation of cancer stem cells (CSCs, CD90+, and CD24+) through the activation of WNT signaling." (PMID 26539408, 2015). "However, when subgroup analysis was performed according to LN status, high CD24 expression was associated with significantly shorter DFS (P = 0.043) and OS (P = 0.012) in early-stage breast cancer for pN0/N1 tumours but not pN2/N3 tumours." (PMID 26444008, 2015). "However, CD44+/CD24-/low/ESA+ does not constitute a universal antigenic phenotype of TICs in all breast cancer subtypes." (PMID 25216750, 2014).